NXPH1 (neurexophilin 1)
Description:
May be signaling molecules that resemble neuropeptides and that act by binding to alpha-neurexins and possibly other receptors.
Synonyms: NPH1; Nbla00697
Tractability: Antibody: UniProt places it where antibodies can reach, with high confidence; UniProt predicts a signal peptide or a membrane-spanning region; its Gene Ontology location is reachable by antibodies, with medium confidence. PROTAC: its protein half-life has been measured.
Gene: Protein-coding gene on chromosome 7 (8,433,609 to 8,752,961, forward strand). Ensembl gene ENSG00000122584.
Subcellular location: Secreted
Gene Ontology:
Molecular function: signaling receptor binding
Biological process: modulation of chemical synaptic transmission
Cellular component: extracellular region; GABA-ergic synapse; glutamatergic synapse; synaptic cleft
Genetic constraint (gnomAD): Loss-of-function variants: 5 observed, 24.69 expected, observed/expected ratio (o/e) 0.2, 90% interval 0.1 to 0.43. The upper end of that interval is the gene's LOEUF score, 0.43, which puts it in group 1 of 6, group 1 being the genes least tolerant of losing a copy. Missense variants: 324 observed, 338.9 expected, observed/expected ratio (o/e) 0.96, 90% interval 0.87 to 1.05. Synonymous variants: 144 observed, 130.16 expected, observed/expected ratio (o/e) 1.11, 90% interval 0.96 to 1.27.
Homologues: Orthologues: chimpanzee NXPH1 (100% identical), mouse Nxph1 (99% identical), pig NXPH1 (99% identical), macaque NXPH1 (99% identical), guinea pig NXPH1 (99% identical), rabbit NXPH1 (99% identical), chimpanzee NXPH1 (94% identical), dog NXPH1 (94% identical), rat Nxph1 (94% identical), zebrafish nxph1 (87% identical), tropical clawed frog nxph1 (87% identical). Paralogues in human: NXPH2 (61% identical), NXPH3 (47% identical), NXPH4 (42% identical).
Diseases named in the same sentence as NXPH1 in open-access papers:
NXPH1 is named in the same sentence as 34 diseases in open-access papers, as found by Europe PMC text mining. Sharing a sentence is not in itself a finding about the gene and the disease. The quoted sentences say what the papers report.
pancreatic cancer (3 papers, 2021 to 2025). "NXPH1 and NXPH2 have been reported to be highly expressed in pancreatic cancer." (PMID 39559360, 2024). "In contrast, there was a negative correlation between lymph node metastasis and NXPH1 in pancreatic cancer." (PMID 34950701, 2021).
schizophrenia (3 papers, 2024 to 2025). A major psychotic disorder characterized by abnormalities in the perception or expression of reality. "The remaining genes (G3bp2, Cpne7, Atcay, Zmat4, and Nxph1) of the unique LS genes are generally understudied in their role in regulating behavior, although Zmat4 is associated with schizophrenia." (PMID 38263132, 2024).
COVID-19 (2 papers, 2023 to 2025). A disease caused by infection with severe acute respiratory syndrome coronavirus 2. "The study found that autoantigens like NXPH-1, PCSK-1, SLC2A10, and DCD correlated with markers of COVID-19 severity like D-dimers, ferritin, C-reactive protein, and lactate which can increase in severe COVID-19." (PMID 36937488, 2023).
diabetes (2 papers, 2017 to 2022). "Specifically, the PPARGC1B and NXPH1 genes have been associated with childhood obesity in Brazil and with diabetes in the Mexican-Mestizo populations respectively." (PMID 28068899, 2017). "Furthermore, eight of the 17 CpG sites reside in genes (FSTL1, SORCS2, NRF1, DLC1, PPARGC1B, CHN2, NXPH1) that have prior known associations with obesity, diabetes, and the insulin pathway." (PMID 28068899, 2017).
pancreatic ductal adenocarcinoma (2 papers, 2022). An infiltrating adenocarcinoma that arises from the epithelial cells of the pancreas. "It has been reported that NXPH1 and 2 are highly expressed in tumor tissues of pancreatic ductal adenocarcinoma with higher malignancy." (PMID 35758021, 2022). "An immunohistochemical study based on pancreatic ductal adenocarcinoma showed a negative correlation between neurexophillin-1 (NXPH1) and T stage of the tumor." (PMID 36468004, 2022).
Type 2 diabetes (2 papers, 2017 to 2024). "In the same GWAS, several SNPs of NXPH1 were associated with type 2 diabetes, blood pressure and plasma LDL-cholesterol, HDL-cholesterol, TG as well as C-reactive protein levels." (PMID 28134766, 2017). "Furthermore, NXPH1 was implicated in the characteristics of Type 2 diabetes among obese Hispanic children in a genome-wide association study." (PMID 39308831, 2024).
Alzheimer disease (1 paper, 2025). A progressive, neurodegenerative disease characterized by loss of function and death of nerve cells in several areas of the brain leading to loss of cognitive function such as memory and language. "Specifically, NXPH1 regulates synaptic plasticity, while CRTC1 has been linked to aging-related disorders such as Alzheimer’s disease and regulates gene expression related to dendritic maturation and inflammation to promote blood–brain barrier integrity, memory, and learning." (PMID 39996777, 2025).
autism (1 paper, 2011). Persistent deficits in social interaction and communication and interaction as well as a markedly restricted repertoire of activity and interest as well as repetitive patterns of behavior. "Furthermore, the NXPH1 interacts with neurexin Iα, a protein that promotes adhesion between dendrites and axons and has been identified to carry variants in autism patients." (PMID 22016809, 2011).
cervix cancer (1 paper, 2021). "NXPH1 and its two downstream receptors, NRXN1 and NRXN3, have established 1722 cell-to-cell communications, accounting for 97.6% of all possible cell-cell links in cervix cancer cell lines." (PMID 35052689, 2021).
Hypercalciuria (1 paper, 2024). "Notably, NXPH1 mediates hematopoiesis, immune responses, and osteoblast activity in the bone marrow, which could be a plausible pathway to explain the common finding of hypercalciuria among brushite stone formers." (PMID 39156495, 2024).
intraductal papillary mucinous neoplasms (1 paper, 2021). "In a study of intraductal papillary mucinous neoplasms (IPMNs), NXPH1 was more likely to be methylated in low-grade dysplasia than in high-grade dysplasia." (PMID 34950701, 2021).
irritable bowel syndrome (1 paper, 2024). Irritable bowel syndrome (IBS) is a chronic functional condition of the lower gastrointestinal (GI) tract characterized by abdominal pain or discomfort and disordered bowel habit (diarrhea, constipation, or fluctuation between the two). "NXPH1 codes for Neurexophilin 1, a secreted protein implicated in irritable bowel syndrome and several neurological conditions." (PMID 39156495, 2024).
lymph node metastasis (1 paper, 2022). "The detection of NXPH1 may be help delineate appropriate surgical margins, and identify lymph node metastasis in imaging studies." (PMID 36468004, 2022).
neuroblastoma (1 paper, 2024). Neuroblastoma (NB) is the most common solid, extracranial childhood tumor. "In neuroblastoma, NXPH1 has been shown to impact tumor growth, metastasis, and patient prognosis." (PMID 39164641, 2024).
prostate carcinoma (1 paper, 2021). A carcinoma that arises from epithelial cells of the prostate gland. "NXPH1 was incorporated in a 10-gene signature that predicted biochemical recurrence for prostate cancer, and its expression level was upregulated in patients with a Gleason score ≥7." (PMID 34950701, 2021).
tumor (6 papers, 2021 to 2025). "The upregulated genes CPLX3 and SPAG6 appeared to be associated with poor survival, whereas the downregulated genes GDPD5, NXPH1, and AHI1 were identified as tumor suppressors." (PMID 34950701, 2021). "The downregulated genes GDPD5, NXPH1, and AHI1 were identified as tumor suppressors, while the upregulated genes CPLX3 and SPAG6 were regarded as oncogenes." (PMID 34950701, 2021).
cancer (2 papers, 2021 to 2025). A tumor composed of atypical neoplastic, often pleomorphic cells that invade other tissues. "In PCa, the sensitivity and specificity for cancer detection were 100% and 91.7% for EMX1, 78.6% and 91.7% for Chr5q14.1, 57.1%, and 91.7% for NXPH1, and reached 100% and 87.5% for the combined triplex methylation score." (PMID 41008642, 2025).
gastrointestinal tumours (1 paper, 2023). "One of these genes is neurexophilin (NXPH1) whose associated NRSE region, NRSE at chr7:8,476,565–8,476,895, showed an opposite DNA methylation pattern between PA and gastrointestinal tumours along the upstream flanking region." (PMID 37301955, 2023).
NXPH1 also shares sentences with these, for which no sentence is quoted: breast carcinoma (5 papers); Obesity (2); anxiety disorder (1); bipolar disorder (1); colorectal cancer (1); depression (1); hippocampal atrophy (1); hypersomnia (1); Infertility (1); insomnia (1); invasive breast carcinoma (1); lung carcinoma (1); mental disorder (1); squamous cell esophagus carcinoma (1); squamous cell head and neck carcinoma (1); type 1 diabetes (1).